CD40 (CD40 molecule)
Diseases named in the same sentence as CD40 in open-access papers (continued):
Sharing a sentence is not in itself a finding about the gene and the disease.
tumor (continued). "Moreover, the anti-tumor efficacy of CD40 agonists in mouse models was greatly improved by engineering Fc variants with enhanced binding to FcγRIIb, including the S267E variant that confers 30-fold increased binding affinity to FcγRIIb." (PMID 33392713, 2021). "In particular, the cross-linking of CD40 by CD40 ligand may promote the progression of different tumor types through the induction of cell motility and migration." (PMID 34445576, 2021). "Finally, CD40-activated APCs produce IL-12 and IL-15, cytokines that are essential for NK cell-mediated killing of tumor cells." (PMID 33392713, 2021). "Our aim was to study the effects of mitazalimab (ADC-1013; JNJ-64457107), a human anti-CD40 agonist IgG1 antibody, on activation of antigen-presenting cells, and how this influences the priming and anti-tumor potential of antigen-specific T cells, in mice transgenic for human CD40." (PMID 33948686, 2021). "The requirement for inoculation with relatively large tumours was hypothesized to be due to the need to provide antigen to CD40 agonist activated DC." (PMID 34960140, 2021). "This study suggested that CD40 agonism may lead to better priming of T cells by APCs when these APCs are loaded with tumor antigens recovered from dying tumor cells." (PMID 34868044, 2021). "Overall, combining CD28 and CD40/CD40L effects within a chimeric CD40L:CD28 design shows promise to deliver CD40 activation to the TME together with improved T cell functionality for tumor attack." (PMID 34912334, 2021). "Moreover, macrophages’ direct ability to lyse tumour cells upon CD40 agonist treatment has been demonstrated in the KPC mouse model." (PMID 34439389, 2021). "Leishmania infections are able to inhibit CD40-induced N-Ras activation as a survival strategy switching CD40 signalling leading to inhibition of the p38MAPK pathway, the master regulator of transcript stability and tumour progression." (PMID 33536086, 2021). "Additionally, combining anti-CD40 mAb with CSF-1R inhibitors potently suppressed tumor growth in an autochthonous poorly immunogenic mouse melanoma model." (PMID 34771482, 2021). "Already in 2011, a study involving mice models and human tissue demonstrated that CD40 agonists could aid at tumor regression in patients with PC by activating macrophages to fight the tumor and by leading to regression of the stroma." (PMID 34680101, 2021). "Thus, ligation of CD40 represents a powerful but context-dependent tool for breaking tolerance against tumor antigens." (PMID 32674488, 2020). "CD40 agonist antibodies may direct tumor cell opsonization and antibody-dependent cellular cytotoxicity (ADCC) to further promote antitumor effects." (PMID 32244756, 2020). "However, the effect of CD40 in mediating the formation of Tscm, especially tumor-specific Tscm, is still unclear." (PMID 32536922, 2020). "The administration of CD40 agonists stimulates the immune state of the tumor site, and CD40-activated macrophages may promote the delivery of chemotherapy in the destructed stroma." (PMID 33505964, 2020). "Anti‐tumor responses have been reported in both mice and humans, and there is a general consensus that CD40 agonist therapy provides the necessary immune‐priming signals to convert the immunogenic cold tumor microenvironment to a desirable hot inflammatory microenvironment." (PMID 32821382, 2020). "Furthermore, the cytokine production by freshly isolated tumor-infiltrating T cells is equally enhanced for MEKi/CD40 Ab and MEKi/PD-1-treated tumors." (PMID 32358491, 2020). "Thus, non-redundant methods of stimulation T cell priming—directly via costimulatory mAbs, or via activation of APCs via CD40 mAb—still reveal the baseline tumor size as a major determinant of response." (PMID 33597954, 2020).
tumor (continued). "Strikingly, upon TLR triggering, response of circulating and tumor‐infiltrating cDC2s was totally abrogated for all markers, except for CD40 on tumor‐infiltrating cDC2s, who already exhibited a high level in unstimulated conditions and couldn't be interpreted." (PMID 33282290, 2020). "Moreover, macrophages isolated from the pancreas of tumor-bearing animals treated in vivo with anti-CD40 mAb were capable of lysing tumor cells in vitro." (PMID 35582441, 2020). "This heterokaryon possesses DC-derived MHC class I, MHC class II, DC-derived co-stimulatory molecules (lymphocyte function-associated antigen 1 and 3, CD-40, ICAM-1) and tumor-derived antigens and all of these molecules represent efficient machinery for antigen processing and cross-presentation." (PMID 32150821, 2020). "Furthermore, more positive results were obtained in tumor-bearing mice treated with a combination of RT, anti-CD40 and anti-CTLA-4/PD-1." (PMID 35582441, 2020). "Based on our experiments in the PDA30364 model, agonist anti-CD40 Abs are more effective than PD-1 blocking Abs in this respect, most likely because of their more profound impact on the immune cell infiltrate in the tumor." (PMID 32358491, 2020). "In addition, the same rate of tumor regression was obtained with anti-CD40 mAb alone as that produced by combination with gemcitabine." (PMID 35582441, 2020). "In addition, all studies demonstrated that combination therapy involving CD40 agonists provided more potent results in terms of tumor growth suppression and extended survival." (PMID 32821382, 2020). "Interestingly, we also observed a significant decrease in numbers of regulatory T cells (Tregs) present in the tumor when CD40 agonist was part of the treatment." (PMID 32821382, 2020). "We sought to investigate whether the combined treatment of IL‐15 and a CD40 agonist antibody may lead to augmented anti‐tumor responses in PDAC." (PMID 32821382, 2020). "In PDAC, tumor cells are CD40-negative, whereas stromal cells express CD40, particularly TAMs." (PMID 33505964, 2020). "CD40 has also direct cytotoxic effects on CD40-positive tumor cells." (PMID 31970590, 2020). "As such, monocytes differentiating in the tumor are a critical component of the PD1 ICB anti-tumor immune response and provide a target for rational combination therapy, including agonistic anti-CD40 antibodies, and can be designed to increase its success rate in survival benefit." (PMID 32690667, 2020). "Furthermore, treatment of PDAC-bearing mice with clodronate abrogated anti-CD40-mediated tumor regression." (PMID 35582441, 2020). "To validate our hypothesis that LAPTM5 acts as a potential tumor suppressor in CD40 high-expressing tumors, we evaluated its prognostic value in the TCGA-GBM cohort." (PMID 32582531, 2020). "Importantly, HDACi have also been shown to increase the expression of costimulatory molecules on the surface of tumor cells, such as CD40, CD80, and 4–1BB." (PMID 32500025, 2020). "Interestingly, higher expression of CD40 and CD80 on cultured tumor‐infiltrating cDC2s and pDCs, respectively, was associated with a worse clinical outcome as they were linked with shorter PFS." (PMID 33282290, 2020). "Oncolysis induced by a recombinant poliovirus-rhinovirus chimera exposed the tumor antigens, while DCs co-cultured with the supernatant from the chimera-infected tumor cells exhibited increased expression of type I IFNs, CD40, CD80, and CD83, suggesting that this virus promotes APC maturation." (PMID 33680911, 2020). "In addition, blocking the binding of CD40/CD40L between Bregs and CD4+ T cells in two different tumor models caused distinct immune responses in terms of Th1/Th2 differentiation and Treg induction." (PMID 33193391, 2020).
tumor (continued). "Combination of a TLR4 agonist, agonistic anti-CD40, and anti-PD-1 improved the survival of mice bearing orthotopic tumors, and studies with additional tumor models suggest that this therapy promotes DC priming of naïve T cells and recruitment of antigen-specific T cells to the TME." (PMID 33584701, 2020). "We showed in the TRAMP-C2 murine syngeneic tumor model that treatment with either an agonistic anti-CD40 antibody alone or IL-15 prolonged animal survival, however the combination of agonistic anti-CD40 with IL-15 produced markedly additive effects when compared with either agent alone." (PMID 32508818, 2020). "Notably, the administration of the anti-CD40 antibody as a single agent was found to increase the frequency of cDC1 and increase maturation markers in tumor-draining lymph nodes in preclinical models." (PMID 33198059, 2020). "If a T-cell response toward IDO1 could be achieved and supported by agonistic CD40 therapy, this would have the dual benefit of targeting tumor endothelial cells and, in IDO1-expressing tumors, malignant cells." (PMID 32231867, 2020). "CD40 molecules are differentially expressed in the process of tumorigenesis and tumor development." (PMID 32411234, 2020). "Interestingly, the use of anti-CD40 alone showed inhibition in tumor growth in the untreated tumor, but the primary tumor grew progressively and mice reached their end point in tumor size, following the IACUC approved protocol." (PMID 32331490, 2020). "Accordingly, the combination of ACT and DC-activating treatments such as TLR or STING agonists, as well as CD40 stimulation and vaccination with viral or tumor antigens, has been found to have implications for the in vivo expansion, persistence and polyfunctionality of infused T cells." (PMID 33101304, 2020). "We found a significant decrease in tumor growth when anti-CD40 was combined with αPD1 ICB." (PMID 32690667, 2020). "Remarkably, while we observed similar responses between the Panc02 and KPC tumor models, the dose of CD40 agonist used in the Panc02 model (five doses of 12.5 μg) was eight times lower than in the KPC model (first dose 200 μg with four consecutive doses of 100 μg)." (PMID 32821382, 2020). "We employed a two-way ANOVA model to assess and visualize the degree of transcriptional variance between agonistic CD40 mAb and isotype control treated tumor endothelial cells, and applied hierarchical clustering to visualize differentially expressed genes as a heatmap." (PMID 32231867, 2020). "Therefore, we analyzed the effect of agonistic CD40 mAb immunotherapy on tumor endothelial cells in vivo." (PMID 32231867, 2020). "Gem combined with the CD40 agonist could induce tumour regression even after circulating macrophages were depleted." (PMID 32061257, 2020). "Hence, our novel data showing a doubling in CD103+ DC in the tumor‐draining lymph nodes support the increased anti‐tumor responses we observed when CD40 was administered." (PMID 32821382, 2020). "However, the use of a CD40 agonist was shown to promote maturation of macrophages and DCs, as well as cross-presentation of tumor antigens to CD8+ T cells, and to facilitate macrophage tumoricidal activity." (PMID 30987642, 2019). "The DCs that were matured with an IFN-containing cocktail only or pulsed with tumour-specific lysate and matured with full cocktail, expressed significantly higher levels of CD40 (p < 0.001 or p < 0.005, respectively) and HLA-DR (p < 0.005) compared to immature DC (data not shown)." (PMID 30283982, 2019). "CD40 agonist treatment resulted in re-education of M2-like macrophages toward an M1-like type with increased antigen presentation capabilities which led to re-establishment of pro-inflammatory microenvironment and a reduction in tumour mass." (PMID 31331034, 2019).
tumor (continued). "Treatment of LMP1/CD40-expressing lymphomatous mice with an anti-PD-L1 monoclonal antibody induced tumor regression with decreased spleen content, activation and proliferation rate of B-cells as well as a marked increase in T-cell activation, as assessed by CD62L and CD44 expression." (PMID 31382969, 2019). "The data was consistent with the hypothesis that CD40 activated pre-existing tumor-reactive TILs, showing that priming can overcome suboptimal T cell reactivity to antigen and induce an immune response with subsequent tumor control." (PMID 30804938, 2019). "We attempted to determine whether leveraging the immune cell changes in the TME mediated by erlotinib with an immunotherapeutic agent like anti-PD-1 or an agonistic CD40 antibody could further stimulate the immune system to exert anti-tumor effects." (PMID 31291990, 2019). "In other cases, “in situ” vaccination using PRR or CD40 agonists may be used to induce a specific immune antitumor response against naturally presented tumor antigens." (PMID 30800125, 2019). "In mouse models of cancer, CSF1R blockades synergize with the agonistic CD40 antibodies to remove inhibitory immune populations and to drive endogenous antitumor immune responses, resulting in improved tumor clearance and significantly lengthened overall survival." (PMID 31805946, 2019). "However, combination with an anti-CD40 antibody significantly enhanced therapeutic efficacy, indicating that additional immune stimulation is required for tumor control in this model." (PMID 31623390, 2019). "In the murine studies that have shown negative effects of IFA on CD8 T cell responses to short peptides, an alternative vaccination approach using a water-soluble adjuvant preparation, including TLR7 agonist imiquimod and CD40 antibody induced more durable immune responses and better tumor control." (PMID 31248461, 2019). "CD40 is a costimulatory receptor molecule on the surface of APCs (DCs), monocytes and tumor cells." (PMID 31708918, 2019). "Recent studies in mice have shown negative effects of IFA as a vaccine adjuvant and have suggested instead that an optimal adjuvant for short peptide vaccines is a TLR agonist plus an agonistic CD40 antibody, which induced strong and durable T cell responses and tumor control." (PMID 31248461, 2019). "Since mCD40L represents a potent tumour cell-specific killing signal, our work not only offers insights into CD40’s biology in normal and malignant epithelial cells, but also provides an avenue for a ‘double-hit’ approach for inflammatory, tumour cell-specific CD40-based therapy." (PMID 31815003, 2019). "Besides, CD40+ tumor patients performed poorer in terms of pathological stage, distant metastasis and clinical prognosis." (PMID 31708918, 2019). "We then investigated whether the CD40 agonist or anti-PD-1 treatment could in combination with erlotinib delay tumor relapse." (PMID 31291990, 2019). "Also, the activation of Tumor Necrosis Factor (TNF) family ligands that expressed on the surface of NK cells with IL-2, IL-15, IL-12, IL-18, and CD40 cytokines production induce NK cell cytotoxicity against tumor target cells and IFNγ production." (PMID 31457012, 2019). "Additionally, we found exceptionally high levels of CD40 on TIL-Bs originating from Bhi tumor samples." (PMID 31623665, 2019). "Tumor volume measurements showed significantly enhanced inhibition in growth for the right flank tumors of mice in the cohort treated with SRBs loaded with CD40 mAbs and IGRT." (PMID 29594038, 2018). "In the same model FAP-IL2v further enhances the efficacy of PD-L1 checkpoint inhibition when combined with an agonistic CD40 antibody resulting in long term survival in the majority of animals, and in the induction of immunological memory as evidenced by protection from tumor cell re-challenge." (PMID 30400822, 2018).
tumor (continued). "This was a reasonable hypothesis, since we have observed that antigen presenting cells in RAG1-/- mice could be activated by injection of anti-CD40 and activate transferred T lymphocytes from tumor bearing donors." (PMID 29975708, 2018). "Herein, we investigated the efficacy of IL-2/CD40 treatment in elderly tumor-bearing mice." (PMID 30560130, 2018). "Furthermore, although we did not detect a significant increase in the expression of costimulatory factors in total CD11c+ DCs, CD40 expression was markedly increased in CD103+ DC population from the tumour-draining LNs from Y27632-treated mice." (PMID 29867097, 2018). "Furthermore, agonists of stimulatory checkpoint pathways such as OX40, ICOS, GITR, 4-1BB, CD40, or molecules targeting tumor microenvironment components like IDO or TLR are under investigation." (PMID 29544515, 2018). "The use of antibodies in the reprogramming of TAM ratios has also proven successful when agonistic anti-CD40 antibodies were administered in combination with gemcitabine, resulting in tumor regression in both mice and human patients with pancreatic ductal carcinoma." (PMID 30349530, 2018). "Recently, an anti-CD40 based vaccine against E7 was able to prime T cells to kill HPV-related tumor cells, suggesting that once cytotoxic T cells are primed against E7 targets, their killing may be optimized to achieve strong tumorcidal efficacy." (PMID 29464051, 2018). "As the age-related differences in TDLN and tumor-infiltrating CD11c+ cells and T cells reported in this study were observed after one-third of the usual IL-2/CD40 schedule, further studies are required to examine CD11c+ cells/DCs and T cells after a complete schedule of IL-2/CD40." (PMID 30560130, 2018). "Examination of tumor-associated T cells showed that IL-2/CD40 reduced young, but not elderly, CD4+ T cell and Treg proportions, leaving elevated Treg proportions in elderly IL-2/CD40-treated tumors, implying increased suppressive activity in elderly tumors." (PMID 30560130, 2018). "Similarly, we have shown that IL-2/anti-CD40-activated macrophages can rescue age- and tumor-induced T cell function in vitro." (PMID 30459812, 2018). "To test if DCs from our donor mice could activate T cells, we isolated dendritic cells from tumor bearing mice and activated these cells ex vivo with anti-CD40, using the same protocol we used for B lymphocytes." (PMID 29975708, 2018). "Collectively, these changes may contribute to the IL-2/CD40-induced slowing of tumor growth observed in both age groups." (PMID 30560130, 2018). "CD40 is a co-stimulatory molecule belonging to the tumor necrosis factor receptor superfamily which can activate both innate and adaptive immune system, making it an interesting target for tumor immunotherapy." (PMID 30400822, 2018). "In order to determine whether CTL activity was altered during aging following macrophage depletion and immunotherapy, we next performed in vivo CTL analyses in AE17sOVA tumor-bearing mice ± IL-2/anti-CD40 immunotherapy ± macrophage depletion." (PMID 30459812, 2018). "Therefore, we envisioned that tumor elimination will be achieved by a combination of CAR-modified T cells with CD40/C40L pathway modifications." (PMID 29329591, 2018). "To test our hypothesis that activated B lymphocytes could present antigens to T cells, we isolated B lymphocytes from peripheral lymph nodes of tumor bearing C57Black/6 mice and stimulated the cells with agonist anti-CD40." (PMID 29975708, 2018). "The results of this study provide evidence that the use of SRBs loaded with immunoadjuvants like anti-CD40 mAbs could enhance both local and metastatic tumor cell kill." (PMID 29594038, 2018). "Additionally, reduced CD25, CD73, and CTLA-4 on tumor-infiltrating CD4+ T cells in both age groups suggest reduced Treg-mediated suppression within IL-2/CD40-treated tumors." (PMID 30560130, 2018).